LCN2 (lipocalin 2)
Diseases named in the same sentence as LCN2 in open-access papers (continued):
Sharing a sentence is not in itself a finding about the gene and the disease.
infection (continued). "Neutrophils secrete LCN2 from their secondary granules to bind bacterial siderophores and limit their iron acquisition, and express NRAMP1 to sequester free iron from serum during infection." (PMID 33926483, 2021). "In contrast, no changes in Lcn-2 levels were measured in MS diet-fed mice during the course of infection." (PMID 32737335, 2020). "Myeloperoxidase (MPO), a marker of neutrophil activity in intestinal mucosa, and lipocalin-2 (LCN-2), a glycoprotein upregulated in tissue damage under infection conditions, have been considered as biomarkers of environmental enteric dysfunction, including EPEC infection in children." (PMID 33392105, 2020). "Neutrophils from Lcn-2–/– animals do not migrate to sites of infection and do no longer respond to chemotactic stimuli, which however can be reverted by the addition of recombinant Lcn-2." (PMID 30641920, 2019). "Mice lacking lipocalin-2 exhibit increased mortality from infection with siderophore-expressing bacteria, such as E. coli, demonstrating the anti-microbial relevance of this bacterial iron withholding system." (PMID 31824960, 2019). "In our early expression setup, where chimeric KO/WT and WT/KO mice were aerosol infected, we saw no expression of Lcn2 prior to day 14 after infection and moreover no migration of neutrophils to the lung tissue was observed at these early time points." (PMID 30534124, 2018). "However, in Tg/eif2ak4−/− mice, a significant increase in fecal lcn-2 level upon AIEC LF82 infection was observed at day 21 post-infection, and this lasted up to day 40 post-infection." (PMID 30120269, 2018). "IL-10KO-derived TEPMs, but not WT-derived TEPMs, expressed Lcn2 after 1-hour infection with E. coli." (PMID 27734904, 2016). "Furthermore, immunocytochemistry showed co-localization of Lcn2 and LC3 in IL-10KO-derived TEPMs 2 hours after infection with E. coli." (PMID 27734904, 2016). "For example, lipocalin 2 is a potent IL-17-target gene that is highly upregulated in Candida-infected tongue tissue, but is not required for mediating immunity to OPC, as Lcn2-/- mice are resistant to infection." (PMID 25849644, 2015). "Our study in mice suggests that lipocalin 2 is not detectable in CSF of non infected mice and can be detected as early as 5 h after infection and before the pleocytosis." (PMID 24885531, 2014). "Lcn-2, an acute-phase protein secreted primarily by neutrophils, macrophages, and epithelial cells in response to inflammatory stimuli, was not sufficient to clearly discriminate between the two infection types." (PMID 41370284, 2025). "We hypothesized that Lcn2 treatment would lead to reduced bacterial burdens during our implant model of S. aureus infection while CXCR2 antagonism would inhibit neutrophil recruitment and therefore increase infection severity." (PMID 38567642, 2024). "Second, we used LPS as the ALI insult, so the role of LCN2 during direct pathogen infection was not evaluated, which may limit the generalizability of our findings." (PMID 36923935, 2023). "To establish whether changes in offspring gut microbiota led to intestinal inflammation, we measured lipocalin-2 (LCN2), a marker of intestinal and metabolic inflammation and infection, and diamine oxidase (DAO), a marker of intestinal mucosal injury, in pup serum." (PMID 36314979, 2022). "Among 106 upregulated and 63 downregulated genes in Lcn2-/- CD103+ DCs, only very few (one and four genes, respectively) showed similar regulation in cells isolated from homeostatic lungs, indicating specific differentially regulated gene sets during homeostasis and infection." (PMID 33905460, 2021). "These LCN2-producing PMN are attracted to the infected mammary gland by the chemotactic molecule interleukin (IL)-8 that is secreted by the bovine mammary epithelium to enhance phagocytosis and reactive oxygen species (ROS) production of PMN to clear the infection present." (PMID 33240956, 2020).
infection (continued). "Importantly, the increased lcn-2 level in LF82-infected eif2ak4−/− mice lasted for at least twenty days, suggesting that a chronic inflammation is set up in eif2ak4−/− mice after AIEC infection." (PMID 30120269, 2018). "Also, when S. tmAvir was used for the secondary infection in AIEC-colonized mice there was a significant reduction in immunopathology, a blunted TNFα release from explanted cecal tissue, and a significant reduction in fecal lipocalin-2 output." (PMID 27711220, 2016). "To further explore this discrepancy, we evaluated Lcn2 expression in WT- and IL-10KO-derived TEPMs infected with E. coli, and found that IL-10KO-derived TEPMs, but not WT-derived TEPMs, expressed Lcn2 after infection with E. coli." (PMID 27734904, 2016). "New proposed definitions integrate biomarkers of structural injury to the kidney which may be able to differentiate more accurately AKI and CKD in populations without known kidney function prior to infection (e.g., urine neutrophil gelatinase-associated lipocalin (NGAL), also known as lipocalin-2)." (PMID 36737313, 2023). "In addition, as confirmed infection was not retrieved in preterm babies, a limitation of our study is that LCN2 was related to infection/inflammation markers but not directly with infection and, thereby, we cannot conclude a clear correlation between LCN2 production and infection in preterm infants." (PMID 37496672, 2023). "Nonetheless, contrary findings have also been reported, in that Lcn2 exerted no influence neutrophil recruitment and activation in mice at 24 h post-infection with Klebsiella pneumoniae, which could be attributable to differences in the models and analytical methods used among different studies." (PMID 31375129, 2019). "In addition to the possible supplementation of patients with recombinant LCN2 in an effort to restore the hypoferremia of infection and to sequester bacterial siderophores, LCN2 could be designed to bind additional siderophores not already accommodated by its native structure." (PMID 36054235, 2022). "As IL6 levels are low for S.Tm infected mice, we also determined plasma Lipocalin-2 (LCN2), as an acute phase protein produced upon infection with Gram-negative bacteria." (PMID 34368018, 2021). "Infection of both Tg/eif2ak4+/+ and Tg/eif2ak4−/− with the K12 MG1655 strain did not induce any significant change in fecal lcn-2 level up to 40 days post-infection." (PMID 30120269, 2018). "In addition to lipocalin-2, equine MSCs from all sources examined expressed the immunomodulatory genes, MCP-1, IL-6, IL-8, and CCL5, suggesting that these cytokines may contribute to the reported ability of equine MSCs to limit infection indirectly by recruiting and activating immune cells." (PMID 30044182, 2018). "Although, the aim of the current study was not to identify biomarkers, the concomitant increase in LCN2, CRP and IL6, that we found in this study, might aid in recognizing preterm infants experiencing infection." (PMID 37496672, 2023).
kidney disease (222 papers, 2009 to 2026). "Lipocalin-2 is a neutrophil-associated protein that has a key role in immune function, and it is linked to cardiovascular and renal diseases." (PMID 38610889, 2024). "This triggers an exaggerated production of lipocalin 2 (Lcn2)—a small iron-transporting protein largely produced by kidney tubular cells, following cellular damage, that is associated with kidney disease progression and other metabolic disorders." (PMID 36231140, 2022). "Lcn2 is a well-known biomarker of kidney disease and causes renal damage by inducing apoptosis of RTECs." (PMID 34236049, 2021). "These dysfunctions are associated with an exaggerated production of LCN2—a small iron-transporting protein associated with kidney disease progression and metabolic disease." (PMID 34524466, 2021). "Second, the study included only healthy individuals and the LCN2 variants in the serum, plasma and urine should be explored in human subjects with metabolic, cardiovascular, and renal diseases." (PMID 34938273, 2021). "Interestingly, this gene encodes for Lipocalin 2, that behaves as a driver of kidney disease progression." (PMID 36167809, 2022). "The localized effect of LCN2 deficiency in MRL/lpr mice was surprising, as cutaneous and neuropsychiatric diseases improved but systemic and kidney disease were unaffected." (PMID 39399497, 2024). "In regard to their potential to identify disease and its progression, patients with kidney diseases have higher levels of urinary adiponectin, lipocalin-2, leptin, galectin-3 and IL-6." (PMID 37189804, 2023). "An increase in urinary lipocalin-2 amounts was noticed in diabetic patients with clinical signs of renal diseases." (PMID 37189804, 2023). "Accordingly, either Lcn2 gene inactivation or the pharmacological blockade of NGAL have notably proven to ameliorate and prevent the fibrotic and inflammatory responses elicited in humanized in vitro and in vivo models of heart and kidney diseases." (PMID 36510294, 2022). "The excess lipocalin-2 in kidney disease increases bone production of FGF23 and serum FGF23 levels, which contributes to the progression of the disorder." (PMID 36157448, 2022). "As reported here, NGAL/LCN2 plays a major role in end-organ damage and organ fibrosis in both cardiac- and renal-disease models." (PMID 33510370, 2021). "In contrast, we detected Lcn-2 to be protective in an inflammatory kidney disease model, namely NTS." (PMID 23861783, 2013). "The role of Lcn-2 in inflammatory driven kidney diseases such as nephrotoxic serum nephritis (NTS) is so far unclear." (PMID 23861783, 2013). "LCN2 is not only a marker, but also a key contributor of kidney disease, as reflected by the alleviation of chronic kidney damage in mice with Lcn2 gene deletion." (PMID 22514649, 2012). "Likewise, among the proteins detected in higher abundance, lipocalin 2 (Lcn2) or neutrophil gelatinase-associated lipocalin (NGAL) and the serine protease inhibitor A3N (Serpina3n), are related to the progress of kidney diseases." (PMID 40582410, 2025). "Lcn2 is a highly sensitive, but unspecific, tissue damage marker, whereas Kim‐1 expression is the highest in the kidney proximal tubules and they have been found to be increased in different types of human kidney disease." (PMID 40018982, 2025). "Similarly, uPA, EGF, and Lipocalin-2 have demonstrated involvement in the pathology of renal disease." (PMID 35355862, 2022). "Therefore, serum LCN2 emerges as a major kidney-bone crosstalk molecule that links the inflammation of kidney disease to FGF23 secretion from the bone and the development of cardiac disease during CKD." (PMID 34334787, 2021). "High concentrations of LCN2 are found in the serum of patients with rheumatic and kidney diseases." (PMID 31151292, 2019). "Furthermore, Kim-1 and Lcn2 were specifically induced in animal models and human renal diseases that involve acute injury of the proximal tubule epithelium." (PMID 27983637, 2016).
kidney disease (continued). "Understanding the mechanisms that regulate genes, such as Lcn-2, related to cytoprotective pathways could offer new perspectives for more efficient therapy of renal disease." (PMID 26911537, 2016). "We found that lcn2, cfi, pla2g7, and ier3 were upregulated by kidney disease progression." (PMID 22970174, 2012). "In addition to the role as a marker for renal disease, LCN2 is a contributory factor as well." (PMID 40171220, 2025). "Kidney expression of Lcn2 in injured kidneys originates mainly from the distal tubules and is upregulated particularly in response to toxic or ischemic injuries, while Kim‐1 is upregulated especially during ischemic acute tubular necrosis, and to a lesser degree in other kidney diseases." (PMID 40018982, 2025). "Furthermore, the strong induction of lipocalin‐2 (LCN2) in the R186S kidneys may provide a link between ER stress, inflammation, and fibrosis, as LCN2 is a known homing factor for inflammatory cells and an active player in kidney disease progression." (PMID 37885358, 2023). "However, the role of bone-derived LCN2 (the major producer of resting LCN2) in renal diseases remains unclear." (PMID 36353239, 2022). "However, the role of bone-derived LCN2 in kidney diseases warrants further investigation." (PMID 36353239, 2022). "Lipocalin 2 (LCN2) or NGAL is one of the most promising and investigated biomarkers of kidney disease." (PMID 39055699, 2024). "Studies have shown that both Kim-1 and Lcn2 are induced in AKI animal models and human renal diseases that involve acute injury of the proximal tubule epithelium." (PMID 28860665, 2017). "Emerging evidence proposes that LCN2 is not merely a biomarker of cardiac and renal diseases, but has a role in modulating chronic inflammation and other processes that can lead to these diseases." (PMID 33603000, 2021). "Supporting a more generalized role of the UPR transducers in renal disease, the PERK pathway, through the expression of lipocalin 2, regulates tubular cell viability upon proteinuric stress, and lipocalin 2 when secreted in urines can provide prognostic information." (PMID 32303684, 2020). "Anti-nuclear antibodies and kidney disease were not affected by LCN2." (PMID 39399497, 2024). "We could not investigate relations between kidney disease (for which LCN2 is considered to be a promising biomarker), peripheral LCN2, and CSF LCN2 further." (PMID 32001681, 2020). "In contrast, we report that the severity of kidney disease was similar in the Col4a3KO mouse model of progressive CKD, with and without global deletion of Lcn2." (PMID 34334787, 2021).
bacterial infection (141 papers, 2010 to 2026). "Another interesting molecule with consistent upregulation was LCN2, which primarily sequestrates free iron, thus limiting its availability to bacteria, and Lcn2−/− mice exhibit an increased susceptibility to bacterial infections." (PMID 40512033, 2025). "Previous studies have reported that LCN2 has an optimal diagnostic performance in discriminating viral and bacterial infections, suggesting that LCN2 is a potential biomarker for clinical diagnosis." (PMID 37317134, 2023). "Lipocalin-2 (LCN-2, also called neutrophil gelatinase-associated lipocalin) is a 25 kDa protein that plays a role in the innate immune response to bacterial infection." (PMID 35056647, 2022). "Other markers of bacterial infection, such as neutrophil gelatinase-associated lipocalin-2 (NGAL) and resistin, have shown promise across a range of clinical settings but have not been integrated in clinical practice yet." (PMID 34395340, 2021). "Bacterial infection and upregulation of LCN2 are mutually linked since application of lipopolysaccharides boosts LCN2 expression." (PMID 34884961, 2021). "We showed that Lcn2−/− mice exhibited increased susceptibility to bacterial infections, in keeping with the proposed function of Lcn2 in iron sequestration." (PMID 31781104, 2019). "Experimental findings have shown that the loss of LCN2 is correlated with a higher susceptibility to bacterial infections and more severe hepatic damage after challenge with appropriate hepatotoxins." (PMID 27729871, 2016). "Along this line it has been shown that mouse LCN2 (mLCN2) is overexpressed during the early stage of a bacterial infection and that mLCN2-deficient mice are significantly more sensitive to bacterial infections." (PMID 26635366, 2016). "Neutrophil gelatinase-associated lipocalin (Ngal) (also known as Lcn2) is expressed in neutrophils and also in solid organs, where it is thought to provide protection against bacterial infection by sequestration of iron, thereby limiting bacterial growth." (PMID 25959381, 2015). "Neutrophil gelatinase associated lipocalin (NGAL), or lipocalin 2, is a secreted glycoprotein that has an immune function to protect against bacterial infection." (PMID 24743777, 2014). "It has also been reported that lipocalin-2-deficient mice have increased bacterial infections in the urinary tract." (PMID 23940770, 2013). "Lipocalin 2 has also been implicated in innate immunity, as Lcn2-deficient mice are more susceptible to bacterial infection." (PMID 21423737, 2011). "However, LCN2 can sequester iron during bacterial infections to reduce the proliferation of pathogenic bacteria and initiate wound healing." (PMID 39598420, 2024). "On the other hand, decreased LCN2 levels as well as decreased neutrophilia might increase susceptibility to bacterial infection." (PMID 37386145, 2023). "The protein encoded by LCN-2 (lipocalin 2) performs an essential role in the immune response by limiting bacterial growth and lcn2-deficient mice showed increased susceptibility to bacterial infection and a significant reduction in female fertility." (PMID 38352249, 2023). "Consequently, complete or hepatocyte-specific ablation of the Lcn2 gene is associated with higher susceptibility to bacterial infections." (PMID 34884961, 2021). "Indeed, Lcn2-deficient (Lcn2−/−) mice were more sensitive to bacterial infection than wild-type (WT) mice and exhibit higher mortality rates after systemic administration of E. coli." (PMID 31781104, 2019). "In addition, LCN2 deficiency in mice leads to increased susceptibility to bacterial infections." (PMID 38607002, 2024). "Lipocalin-2 (Lcn2) is an important molecule that prevents bacterial infection by sequestering iron ions, and E. coli induces the expression of Lcn2 in the endometrium." (PMID 40364840, 2025). "Lipocalin-2 (LCN2) is a prominent antimicrobial protein released during bacterial infections that limits bacterial access to iron by sequestering siderophores." (PMID 40996229, 2025).